TRIB2 (tribbles pseudokinase 2)
Diseases named in the same sentence as TRIB2 in open-access papers (continued):
Sharing a sentence is not in itself a finding about the gene and the disease.
liver cancer (continued). "Xu and coworkers reported that TRIB2 suppressed the Wnt/TCF4 pathway through several E3 ligases, including β-TrCP, COP1, and Smurf1, in liver cancer cells." (PMID 39199296, 2024). "Tribbles homolog 2 (TRIB2), a substrate of β-TrCP1, reciprocally inhibits β-TrCP1 activity by protein–protein interaction to stabilize YAP in liver cancer cells." (PMID 37686524, 2023). "Mechanistically, TRIB2 enhances nuclear co-accumulation of β-TrCP E3 ligases and β-catenin, promoting the destabilization of β-catenin and TCF4 in liver cancer." (PMID 37686524, 2023). "Here, we reveal that in liver cancer cells, PCBP2 facilitates the TRIB2-induced reduction in global K48-Ub levels by elevating the activity of PSMB5, one of the major components of the proteasome that contains active sites." (PMID 33414446, 2021). "In conclusion, we’ve established a model emerges in which TRIB2 cooperates with and stimulates PCBP2 to reduce the global K48-Ub level in liver cancer cells." (PMID 33414446, 2021). "In conclusion, we elucidated a novel role of TRIB2 to desensitize ferroptosis via E3 βTrCP, by which facilitates TFRC ubiquitiation and finally decreases labile iron in liver cancer cells." (PMID 34315867, 2021). "TRIB2 is specifically activated by Wnt pathway effectors TCF4 and β-Catenin in the human liver cancer cell line HepG2." (PMID 34070799, 2021). "Mechanistically, glutathione peroxidase 4 functioned as one of the terminal effectors of TRIB2 and PCBP2 to protect liver cancer cells from oxidative damage." (PMID 33414446, 2021). "The Wnt/β-catenin/TCF4 pathway promotes TRIB2 expression in liver cancer cells, and in this case TRIB2 also produces a negative feedback, via TRIB2-mediated ubiquitination and degradation of TCF4 and β-catenin through the E3 ligase binding region." (PMID 34070799, 2021). "The interaction and function between TRIB2 and PCBP2 was also investigated in liver cancer cells." (PMID 33414446, 2021). "Furthermore, TRIB2 has been revealed to interact with E3s including Smurf1, COP1, and βTrCP in liver cancer cells." (PMID 34315867, 2021). "Given that E3, Ub, and TRIB2 are all critical factors that belong to the UPS, patients bearing liver cancer might benefit from ferroptosis-based therapy following appropriate modulation of UPS." (PMID 34315867, 2021). "A significant correlation between TRIB2 and PCBP2 was revealed in liver cancer specimens." (PMID 33414446, 2021). "However, whether TRIB2 interacts with PCBP2 to regulate Ub levels and how this interaction influences the viability of liver cancer cells under OS remain unclear." (PMID 33414446, 2021). "Thus, TRIB2 and PCBP2 maintain liver cancer cells viability via GPX4 to protect them against OS." (PMID 33414446, 2021). "However, whether TRIB2 has other functions to boost tumorigenesis in liver cancer cells is still not very clear." (PMID 34315867, 2021). "Interestingly, we also found that even in the absence of TRIB2, erastin, and RSL3 still lift labile iron level in liver cancer cells." (PMID 34315867, 2021).
colorectal cancer (13 papers, 2011 to 2025). A primary or metastatic malignant neoplasm that affects the colon or rectum. "In colorectal cancer, it has been described that the pseudokinase domain of TRIB2 interacts with AP4 and enhances AP4-mediated reduction of p21 expression, ultimately leading to decreased senescence and apoptosis of tumour cells." (PMID 34070799, 2021). "In agreement, TRIB2 levels in colorectal cancer were inversely correlated with survival rate of CRC patients, and positively correlated with tumor grade." (PMID 34198908, 2021). "One year later, it was further confirmed that TRIB2 was overexpressed in colorectal cancer patients, in primary tumor samples obtained from surgical resection, prior to receiving any kind of chemotherapy or radiotherapy." (PMID 34198908, 2021). "p21 is closely involved in the attenuation of cancer cell stemness and the enhancement of the radiotherapy response, and TRIB2 can regulate p21 via interaction with AP4 in colorectal cancer." (PMID 34586732, 2021). "In the present study, we found that TRIB2 was overexpressed in colorectal cancer and inversely correlated with survival rate of CRC patients." (PMID 30541550, 2018). "The expression of TRIB2 in colorectal cancer tissues and adjacent tissues was detected by immunohistochemistry and RT-PCR." (PMID 30541550, 2018). "In colorectal cancer, TRIB2 is observed to block cell senescence through ap4/p21 signaling." (PMID 39963268, 2025). "In colorectal cancer, TRIB2 interacts with AP4 protein through the pseudokinase domain." (PMID 34070799, 2021). "Interestingly, recent literature has reported that high-TRIB2 expression correlated with a worse clinical outcome of colorectal cancer (CRC)." (PMID 30541550, 2018). "In summary, we noted the oncogenic effect of TRIB2 in human colorectal cancer." (PMID 30541550, 2018). "However, the role of TRIB2 in cellular senescence of colorectal cancer (CRC) and its molecular mechanism remains unclear." (PMID 30541550, 2018). "In cellular models of colorectal cancer (CRC), TRIB2 blocks cellular senescence by promoting transcriptional activity of AP4 and p21 repression." (PMID 34070799, 2021). "In this review, we discuss the state-of-knowledge for TRIB1, TRIB2 and TRIB3 in the development and progression of colorectal cancer." (PMID 34198908, 2021). "Tribbles pseudokinase family members (TRIB1 (C8FW or SKIP1), TRIB2 (C5FW) and TRIB3 (NIPK, SKIP3 or LKW)) might be biomarkers of interest in colorectal cancer." (PMID 34198908, 2021).
glioblastoma (11 papers, 2020 to 2024). The most malignant astrocytic tumor (WHO grade IV). "From GFN modules, we identified one glioblastoma neoplastic cell marker, TRIB2 (Tribbles Pseudokinase 2) from CID‐40." (PMID 35044082, 2022). "Our study showed specificity of TRIB2 expression in glioblastoma neoplastic cells." (PMID 35044082, 2022). "In Glioblastoma (GBM), Trib2 interacts with MAP kinase kinase kinase 1 (MAP3K1) and enhances resistance to temozolomide (TMZ) chemotherapy and radiotherapy." (PMID 33794905, 2021). "TRIB2 had also showed its potential as a combined biomarker in concurrence with other proteins, such as BCL2 in AML or MAP3K in glioblastoma." (PMID 34070799, 2021). "LIMD1 and TRIB2 are poorly characterized genes in glioblastoma, and regulation mediated by the A3AR has not been reported." (PMID 38794149, 2024). "Combined elevation of TRIB2 and MAP3K1 could be used as novel prognostic biomarkers to evaluate the malignancy and long-term outcomes of glioblastoma." (PMID 34070799, 2021).
myeloid leukemia (10 papers, 2013 to 2025). A clonal proliferation of myeloid cells and their precursors in the bone marrow, peripheral blood, and spleen. "Trib2 is a cancer-associated pseudokinase that can be induced by mitogens and enhances the propagation of several cancer cells, including myeloid leukemia, liver, lung, skin, bone, brain, and pancreatic." (PMID 33794905, 2021). "Overall, these results showed that Trib2 deficient myeloid leukaemia cells have compromised basal- and induced-MAPK signalling activation." (PMID 29670085, 2018). "Thus, TRIB2 deficiency conferred resistance to daunorubicin treatment by promoting growth and survival advantage in myeloid leukemia cells." (PMID 34070799, 2021). "However, Trib2 deficiency enhanced myeloid leukaemia cell proliferation and survival in both steady state and stress conditions." (PMID 29670085, 2018). "In this study, we investigated the impact of Trib2 deficiency in myeloid leukaemia." (PMID 29670085, 2018). "The impact of Trib2 deficiency in myeloid leukaemia is not well understood." (PMID 29670085, 2018). "However, low TRIB2 expression is associated with subgroups of myeloid leukaemia." (PMID 29670085, 2018). "TRIB2 has been shown to activate p38, thereby reducing the chemotherapy resistance and disease progression of myeloid leukemia." (PMID 39963268, 2025). "In response to stress, TRIB2 as a tumor suppressor stimulates activation of p38 stress signaling in myeloid leukemia." (PMID 33794905, 2021). "The wealth of conflicting studies highlights the need and importance of carefully approaching the analysis of TRIB2 function, as it exerts a dual role in myeloid leukemia and liver in a context-specific manner." (PMID 34070799, 2021). "Together, these results demonstrate that Trib2 expression is required for the appropriate cell cycle stress response and the effective killing of myeloid leukaemia cells." (PMID 29670085, 2018). "We show here the defective stress response manifests a chemotherapy resistant phenotype and a growth advantage to myeloid leukaemia revealing, for the first time, TRIB2 as a tumour suppressor in myeloid leukaemia." (PMID 29670085, 2018). "Summarising, this work identified a novel Trib2-p38 regulatory pathway important for cell cycle checkpoint and stress responses, with implications on drug resistance and relapse in myeloid leukaemia." (PMID 29670085, 2018). "Our results showed a higher number of cell divisions in the Trib2−/− NH9 cells compared to the WT NH9 cells, indicating that Trib2 negatively regulates myeloid leukaemia cell proliferation." (PMID 29670085, 2018). "Data from us and others would conclude that Trib2 exerts a dual role in myeloid leukaemia and other cancers (e.g., T cell leukaemia, liver), in a stage- and context-specific manner." (PMID 29670085, 2018). "We showed that Trib2 is transcriptionally upregulated in the WT myeloid leukaemia cells after either starvation or genotoxic challenge." (PMID 29670085, 2018). "Our data provide evidence for a tumour suppressor role of Trib2 in myeloid leukaemia via activation of p38 stress signalling." (PMID 29670085, 2018). "We previously showed that ectopic Trib2 expression cooperates with Homeobox transcription factor Hoxa9 to accelerate myeloid leukaemia development in mice." (PMID 29670085, 2018). "Trib2 transformed GMPs produced a fully penetrant myeloid leukaemia with fast kinetics and an immunophenotype consistent with a maturing myeloid cell (L-GMP)." (PMID 29599919, 2018). "We measured relative TRIB2 protein expression at specific cell cycle phases using a myeloid leukaemia cell line, SB1690CB." (PMID 27563873, 2016). "TRIB2 may also indirectly activate MAPKs, such as p38, which control cell cycle regulators that are aberrantly activated in myeloid leukemia, exerting a tumour suppressor function." (PMID 34070799, 2021).
myeloid leukemia (continued). "However, ectopic expression of Trib2 alone in 32D cells (an IL-3-dependent myeloid leukemia cell line), or in TF-1 cells, induces a strong apoptotic response." (PMID 30266989, 2019). "Thus, we interrogated the activation status of the MAPKs ERK, p38 and JNK in WT and Trib2-/- myeloid leukaemia cells." (PMID 29670085, 2018). "To assess the impact of Trib2 deficiency on myeloid leukaemia cell survival, we measured the level of apoptosis following growth factor deprivation (GFD) and myeloid leukaemia-based chemotherapy (daunorubicin (DNR)) in the WT and Trib2-/- NH9 cells by flow cytometry using AnnexinV/DAPI staining." (PMID 29670085, 2018). "The physiological role of Trib2 in myeloid leukaemia is not well understood." (PMID 29670085, 2018). "It remains to be investigated whether Trib2−/− progenitors in BM will be refractory to myeloid leukemia development owing to the tumor suppressive function of accumulated C/ebpα." (PMID 27550848, 2016). "In conclusion, our study indicates that miR-99a may play an oncogenic role by targeting the tumor suppressors CTDSPL and TRIB2 in most pediatric myeloid leukemia." (PMID 24191888, 2013). "Similarly, TRIB2 also activates the p38 MAPK pathway in myeloid leukemia." (PMID 34070799, 2021). "Trib2 by regulating the degradation of E3 ubiquitin ligase βTrCP, COP1, and Smurf1 can inhibit the Wnt pathway and reduce cell propagation in myeloid leukemia." (PMID 33794905, 2021). "We demonstrate that Trib2 is not required for the initiation of myeloid leukaemia, but is required for p38 and stress signalling, induction of cell cycle checkpoint response and apoptosis." (PMID 29670085, 2018). "Furthermore, TRIB2 seems not to be necessary for the initiation of myeloid leukemia, but is required for p38 MAPK signalling, a pathway that is activated in cellular stress conditions and regulates cell proliferation." (PMID 34070799, 2021). "Therefore, impaired p38 activation due to the absence of Trib2 most likely accounts for the defective signalling response and chemoresistant phenotype of myeloid leukaemia cell." (PMID 29670085, 2018). "It is not understood how the absence of Trib2 expression affects myeloid leukaemia." (PMID 29670085, 2018).
acute lymphoblastic leukemia (9 papers, 2016 to 2021). Leukemia with an acute onset, characterized by the presence of lymphoblasts in the bone marrow and the peripheral blood. "This tumour suppressive role of the TRIB2-p38 axis is also supported by the evidence that TRIB2 deficiency accelerates the onset of acute lymphoid leukemia." (PMID 34070799, 2021). "In an experimental murine T-cell acute lymphoblastic leukemia (T-ALL) model, Trib2−/− mice had reduced latency in vivo, which associated with impaired MAP kinase (MAPK) activation." (PMID 27462446, 2016). "Mutations in human Trib2 are associated with increased levels of C/EBP in undifferentiated cancers like T-cell acute lymphoblastic leukemia (T-ALL), hence it is unsurprising that trbl mutations have been uncovered in screens for regulators of tumor formation in Drosophila." (PMID 33672471, 2021). "Although TRIB2 function is fundamental in lymphoid lineage, it is associated with both acute myeloid (AML) and acute lymphoblastic leukemias (ALL)." (PMID 34070799, 2021). "Trib2 is highly expressed in human T cell acute lymphoblastic leukemia (T-ALL) and is a direct transcriptional target of the oncogenic drivers Notch and TAL1." (PMID 27191957, 2016). "In human T cell acute lymphoblastic leukemia (T-ALL), NOTCH, PITX and TAL1 are also found to up-regulate TRIB2." (PMID 30541550, 2018). "Like Drosophila Trbl, Trib2 protein requires an intact kinase domain to poly-ubiquitinate CDC25 isoforms and, consistent with the notion that Trib2 controls the cell cycle, Trib2 levels oscillate to establish a G1/M gate in mitotically synchronized T-cell acute lymphoblastic leukemia (T-ALL) cells." (PMID 33672471, 2021).
glioma (8 papers, 2015 to 2024). A benign or malignant brain and spinal cord tumor that arises from glial cells (astrocytes, oligodendrocytes, ependymal cells). "However, the underlying mechanisms for the glioma‐promoting functions of TRIB2 require further investigation." (PMID 31318172, 2020). "Additionally, TRIB2 and MAP3K1 overexpression was associated with the histological grade of glioma (χ2 = 18.86, P < 0.01 for TRIB2 and χ2 = 38.06, P < 0.01 for MAP3K1)." (PMID 31318172, 2020). "The results demonstrated that MAP3K1 is one of the most closely associated genes with TRIB2 in glioma, indicating that MAP3K1 might be functionally regulated by TRIB2 and could be used as a potential combined biomarker for glioma." (PMID 31318172, 2020). "However, the functional role of TRIB2 and the underlying mechanism in glioma are poorly elucidated." (PMID 31318172, 2020). "Since TRIB2 was identified as an essential oncogene in a variety of cancer types, we focused on TRIB2 for further characterization of glioma in this study." (PMID 31318172, 2020). "IHC was performed on 91 glioma samples to analyze the expression of TRIB2 and MAP3K1, and three brain tissues from epilepsy surgery were used as negative controls." (PMID 31318172, 2020). "We found that patients with glioma and lower expression of TRIB2 or MAP3K1 exhibited prolonged overall survival compared with patients with glioma and higher TRIB2 or MAP3K1 expression." (PMID 31318172, 2020). "Additionally, TRIB2 was identified as a glioma neoplastic cell marker by single-cell RNA-seq analysis of GBM samples." (PMID 38827949, 2024). "Lastly, we showed the identification of a glioma neoplastic cell marker, TRIB2, from single‐cell RNA‐seq data analysis, which could potentially become a drug target to tackle tumour heterogeneity challenges." (PMID 35044082, 2022). "Additionally, TRIB2 was identified as a glioma neoplastic cell marker in single‐cell RNA‐seq of GBM samples." (PMID 35044082, 2022). "TCF4 in glioma cells mainly acts in the Wnt/β-catenin-signaling pathway and interacts with TRIB2." (PMID 36231068, 2022). "Interestingly, our survival analysis showed that patients with glioma and increased expression of TRIB2 and MAP3K1 exhibited worse responses to TMZ and radiotherapy." (PMID 31318172, 2020). "In addition, the patients with glioma were divided into two groups according to the GIS of TRIB2 and MAP3K1 expression." (PMID 31318172, 2020). "Moreover, a combined increase in TRIB2 and MAP3K1 in glioma is associated with a poor prognosis and therapeutic resistance to TMZ and radiotherapy." (PMID 31318172, 2020). "Correlated overexpression of TRIB2 and MAP3K1 could be associated with high‐grade glioma." (PMID 31318172, 2020). "In this study, we identified tribbles pseudokinase 2 (TRIB2) as one of the genes that is most correlated with pathological classification, radioresistance, and TMZ resistance in glioma." (PMID 31318172, 2020). "Overall, this study demonstrated the potential of TRIB2 and MAP3K1 as therapeutic targets in glioma." (PMID 31318172, 2020). "Next, combined overexpression of TRIB2 and MAP3K1 was identified in glioma and correlated with a poor prognosis of glioma with significant sensitivity and specificity." (PMID 31318172, 2020). "Survival data of 78 patients who received radiotherapy were extracted, and the Kaplan‐Meier analysis showed that high expression of TRIB2 and MAP3K1 was conversely correlated with the poor survival of patients with glioma who were treated with radiotherapy." (PMID 31318172, 2020). "The data indicated that TRIB2 and MAP3K1 were likely to be enriched in GBM and grade III glioma (TRIB2High/MAP3K1High samples accounted for 72.09% in GBM and 63.16% in grade III glioma) compared with grade I and grade II glioma." (PMID 31318172, 2020). "TRIB2 and MAP3K1 were identified as genes that are correlated with the pathology and survival of glioma." (PMID 31318172, 2020).